CASP4 (caspase 4)
Diseases named in the same sentence as CASP4 in open-access papers (continued):
Sharing a sentence is not in itself a finding about the gene and the disease.
Salmonella Infections (9 papers, 2013 to 2025). Infections with bacteria of the genus SALMONELLA. "For example, the cysteine protease encoded by the Casp4 gene is a key biomarker for Salmonella infection." (PMID 40492727, 2025). "GBP1-deficient cells were also unable to cleave and activate caspase-4 upon LPS transfection or Salmonella infection (p32 fragment)." (PMID 32581219, 2020). "Various studies have investigated the potential of caspase-4 to initiate innate immune responses to intracellular Salmonella infection or Salmonella-derived pathogen associated molecular patterns." (PMID 31096680, 2019). "It has been recently demonstrated that the Casp1−/− mice used in this study are also deficient in Casp11 (also referred to as Casp4), and that Casp11 deficiency in the context of Casp1 deficiency is protective against Salmonella infection." (PMID 23977202, 2013). "Similarly to Salmonella infection, LPS transfection only caused cell death in IFNγ-primed HeLa and was completely abrogated by deletion of CASP4 or GSDMD." (PMID 32581219, 2020). "Caspase-4/5 has an established role for intestinal epithelial cell shedding during Salmonella infection." (PMID 36191054, 2022). "We observed a role for epithelial cell Caspase-4 as well as Caspase-3 in regulating cell death during Salmonella infection in the presence of PMNs." (PMID 36191054, 2022). "A proteomic screen identified and validated CASP7 as a substrate of CASP4 in cells, and we recently demonstrated that CASP3 is activated in a CASP4/5-dependent manner in response to LPS transfection and Salmonella infection." (PMID 38837391, 2024). "It is tempting to speculate that the loss of GBP2 led to the expansion of GBP4 in M. Myotis and E. fuscus since, in humans, upon Salmonella infection, GBP1 requires GBP2 and GBP4 to recruit caspase-4 to the surface of the bacteria." (PMID 38357541, 2024). "Other investigators also showed that caspase-4/11 in intestine epithelial cells could act independently of NLRP3 to directly process IL18 and induce pyroptosis during Salmonella infection." (PMID 36436756, 2023). "Deletion of CASP4 or GSDMD did not alter bacterial invasion, but abrogated Salmonella-induced IFNγ-dependent cell death, confirming that Salmonella infection of HeLa cells activates the non-canonical inflammasome in an IFNγ-dependent manner." (PMID 32581219, 2020).
colon carcinoma (8 papers, 2017 to 2025). "Given the high basal expression of caspase-4 in colon cancer cells and given that SSa induces colon cancer-specific apoptosis and triggers caspase-4 cleavage and activation, we hypothesized that altered expression of caspase-4 may be an underlying cause of the selective effects of SSa." (PMID 29245990, 2017). "The investigation also explored the effect of caspase-4 activation and the activation sequences of caspase-2, caspase-8, and caspase-3 on the apoptosis of human colon cancer LoVo and SW480 cells." (PMID 41011202, 2025). "In summary, SS-a induces apoptosis by facilitating the sequential activation of caspase-4, caspase-2, caspase-8, and caspase-3, thereby inhibiting the proliferation of colon cancer cells." (PMID 41011202, 2025). "Two epithelial-derived colon cancer cell lines expressing SDC1 and CASP4 were also susceptible to SCGB3A2-LPS treatment." (PMID 33452234, 2021). "We also demonstrated that sequential activation of caspase-4, 2, and 8 is critical for SSa-induced caspase-3 activation and apoptosis in human colon cancer cells and that caspase-4 acts upstream of SSa-induced DNA damage." (PMID 29849917, 2018). "We examined the expression of caspase-4 in various cancer cells and found that caspase-4 expression was significantly higher in colon cancer cells than in other cancer cells." (PMID 29245990, 2017). "Overall, our data suggest a model in which SSa induces colon cancer cell apoptosis via caspase-4 activation, followed by DNA damage and/or sequential activation of caspase-2, -8, and -3." (PMID 29245990, 2017). "Furthermore, SS-a was found to activate the expression of apoptosis-inducing proteins, including caspase-4, caspase-2, caspase-8, and caspase-3, in colon cancer cells." (PMID 41011202, 2025). "One previous study found that caspase-4 is highly expressed in the lamina propria of colorectal cancer compared with that in normal tissues, indicating that caspase-4 may represent a biomarker of colon carcinoma." (PMID 34568046, 2021). "It is interesting to note that among the top ~50% of SDC1 and among which the top 20% CASP4 high-expressing lung adenocarcinoma and colon cancer patients (out of 503 for lung and 524 for colon, respectively), approximately 20 (lung) and 50 (colon)% of them possess KRAS mutations." (PMID 33452234, 2021). "Therefore, caspase-4 inhibition was correlated with enhanced clonogenic survival in colon cancer cells." (PMID 29245990, 2017). "Because caspase-4 inhibitors (z-LEVD-fmk and Ac-LEVD-CHO) inhibited SSa-induced apoptosis, we examined whether these inhibitors could restore clonogenic survival to SSa-treated colon cancer cells." (PMID 29245990, 2017).
neuroblastoma (8 papers, 2007 to 2024). Neuroblastoma (NB) is the most common solid, extracranial childhood tumor. "Flow cytometry analysis revealed a significant reduction in caspase 4 levels (p < 0.001) in treated neuroblastoma cells in ER stress conditions, suggesting that Vx-809 restores reticular homeostasis." (PMID 39329905, 2024). "Caspase-4 was replicated, and the researchers evaluated the subcellular positioning of endogenous caspase-4 in SK-N-SH neuroblastoma cells." (PMID 36139768, 2022). "Overall, we demonstrate that NF-κB can mediate Fas-induced apoptosis through caspase-4 protease, indicating that caspase-4 is a new mediator of NF-κB pro-apoptotic pathway in neuroblastoma cells." (PMID 25695505, 2015). "Considering Fas/FasL as an important defense system, it is expected to develop a new therapeutic strategy targeting caspase-4 in tumors, especially neuroblastoma cells in human." (PMID 25695505, 2015). "Upregulation of caspase-4 has been demonstrated to mediate apoptosis in human bronchial epithelial cells, human neuroblastoma SKN-SH cells, and human esophageal squamous carcinoma EC109." (PMID 24174975, 2013). "Caspase-4 can function as an ER stress-specific caspase in humans and is primarily activated in ER stress-mediated apoptosis in various types of cells such as human carcinoma HeLa cells and human neuroblastoma SK-N-SH cells." (PMID 32733636, 2020). "In addition, caspase-4 acts upstream of caspase-9 in TM-induced apoptosis in human neuroblastoma SH-SY5Y cells." (PMID 32733636, 2020). "As expected, the SOD1 aggregates of the L84V SOD1-expressing neuroblastoma cells colocalized with caspase-4 (unpublished data), implying caspase-4 might contribute to cell death in our model system." (PMID 17925878, 2007). "In brief, NF-κB mediates Fas-induced cell apoptosis via regulating caspase-4, which transduces death signal from caspase-8 to caspase-3 and PARP in neuroblastoma cells." (PMID 25695505, 2015). "However, caspase-4 can only be activated by ER stress-inducing reagents not by the other apoptotic reagents, and knockdown of caspase-4 by siRNA reduces ER stress-induced apoptosis in neuroblastoma cells." (PMID 22454627, 2012).
non-small cell lung carcinoma (8 papers, 2018 to 2023). A group of at least three distinct histological types of lung cancer, including non-small cell squamous cell carcinoma, adenocarcinoma, and large cell carcinoma. "In our previous studies, we identified caspase-4 as a novel diagnostic tool for non-small cell lung cancer (NSCLC)." (PMID 33014287, 2020). "In our previous study we found circulating and tumor-associated caspase-4 as a novel diagnostic, predictive and prognostic biomarker for non-small cell lung cancer (NSCLC) patients." (PMID 33014287, 2020). "In addition, Michela Terlizzi analyzed changes in lipid metabolism characteristics in CASP4-positive non-small cell lung cancer and found increased palmitic acid and malonic acid in tissues of CASP4-positive patients, which are important for fatty acid biosynthesis and elongation." (PMID 35633405, 2022). "GSDMD, CASP1, CASP4 and CASP5 gene expression are highly increased in PBMCs of non-small cell lung cancer patients and their expression are closely related to the clinical characteristics of patients." (PMID 37194012, 2023).
atherosclerosis (7 papers, 2021 to 2025). A disease characterized by the build-up of fatty material and calcium deposition in the arterial wall resulting in partial or complete occlusion of the arterial lumen. "However, the present study in ECs investigated the role of the NF-κB-caspase-4/5-mediated pathway in association with GSDM-D in pyroptosis during atherosclerosis." (PMID 39770410, 2024). "The evidence from public databases and ox-LDL-treated macrophages indicate that caspase-4/11-gasdermin D-associated inflammation may be involved in the progression of atherosclerosis." (PMID 33981234, 2021). "Our results are the first of its kind, which showed that the NF-κB-caspase-4/5-GSDM-D pathway regulates pyroptosis in ECs during atherosclerosis." (PMID 39770410, 2024). "In conclusion, this study elucidates the complex interplay between pyroptosis, inflammation, EC dysfunction, and atherosclerosis, mediated via the NF-κB-caspase-4/5-GSDM-D pathway and pyroptotic EVs." (PMID 39770410, 2024). "Tumor spleen Treg and tumor Treg shared one upregulated caspase-4 secretomic pathway, fluid shear stress and atherosclerosis." (PMID 34084175, 2021). "The present study revealed that NF-κB-caspase-4/5-GSDM-D signaling may be one of the crucial mechanistic pathways associated with pyroptosis, and pyroptotic EVs facilitated pyroptosis during atherosclerosis." (PMID 39770410, 2024). "However, SET7 siRNA in atherosclerosis downregulated 57 canonical SGs, 10 caspase 1 SGs, 12 caspase 4 SGs, 81 exosomes SGs, one WBP SG, and two autophagy SGs." (PMID 35320939, 2022). "The inhibition of NF-κB and caspase-4/5 effectively reduced levels of pyroptotic markers and LDH release, suggesting potential therapeutic targets for atherosclerosis." (PMID 39770410, 2024). "Firstly, we explored the role of the NF-κB-caspase-4/5-GSDM-D pathway in endothelial dysfunction and pyroptosis in palmitic acid (PA)-stimulated human umbilical vein endothelial cells (HUVECs) during atherosclerosis." (PMID 39770410, 2024). "The modulation patterns of canonical and exosome secretomes in atherosclerosis, CKD and AAA were similar; and the modulation scales of caspase 4 secretome were bigger than that of caspase 1 secretome in these four diseases." (PMID 35320939, 2022). "The ratios of upregulation versus downregulation of canonical secretome, caspase 1 secretome, caspase 4 secretome, exosome secretome, WPB secretome and autophagy secretome in atherosclerosis, CKD, and AAA were high in atherosclerosis and CKD." (PMID 35320939, 2022).
colitis (7 papers, 2017 to 2025). Inflammation of the colon. "It was shown that GPX8-deficient mice were more susceptible to colitis, and exhibited increased caspase-4/11 activation, with higher levels of caspase-induced inflammation during colitis and septic shock." (PMID 40563487, 2025). "For example, covalent binding between GPX8 and caspase 4 inhibited inflammation associated with colitis, and GPX8 was involved in protection from bleomycin-induced lung injury in IGF1R knockout animals." (PMID 36750850, 2023). "Treatment with NAC, a potent antioxidant, or with VX‐765, a caspase‐4 inhibitor, consistently suppressed caspase 4/11‐dependent inflammasome activation and reduced colitis severity in Gpx8‐deficient mice." (PMID 31782617, 2020). "Collectively, our discovery of a bacterial inhibitor of caspase-4, which is encoded by EHEC NleF, will suggest a new way of thinking about colitis treatment and provide avenues to study EHEC pathogenesis and resulting inflammatory diseases." (PMID 28593173, 2017). "In this case, one could argue that GPx8 acts as a negative regulator; it down-regulates caspase-4 activation and prevents colitis by decreasing caspase-4/11." (PMID 35208621, 2022).
ovarian carcinoma (7 papers, 2018 to 2025). A malignant neoplasm originating from the surface ovarian epithelium. "However, some PYAGs with CNV gain, such as GSDMD, TP63, PRKACA, PJVK and CASP4, showed downregulated mRNA expression in ovarian cancers, and some PYAGs with CNV loss, such as IL18, GPX4, GZMA, NLRP6 and CASP6, showed upregulated mRNA expression in ovarian cancers." (PMID 36707884, 2023). "Further mechanistic analysis indicated that CA induces pyroptosis in ovarian cancer through the CASP4/TXNIP-NLRP3-Gasdermin-D (GSDMD) pathway, thereby inhibiting ovarian cancer cell growth and presenting a potential therapeutic approach." (PMID 40718836, 2025). "Bexarotene, a retinoid X receptor‐selective agonist, provokes pyroptotic cell death in an ovarian cancer cell line by a caspase 4‐GSDME‐dependent signaling cascade." (PMID 37752941, 2023). "A new drug known as 2‐(anaphthoyl)ethyltrimethylammonium iodide (α‐NETA), a choline acetyltransferase inhibitor, hinders the development of epithelial ovarian cancer by activating pyroptosis via the GSDMD/caspase 4 pathway." (PMID 37752941, 2023). "The caspase 4/TXNIP–NLRP3–GSDMD pathway increases pyroptosis in response to treatment with citric acid for ovarian cancer." (PMID 37752941, 2023). "The study showed that bexarotene induced pyroptotic cell death through the caspase-4–GSDME-dependent signaling pathway in an ovarian cancer cell line." (PMID 35778597, 2022). "A clinical setting concentration of bexarotene induced cell death through caspase-4–mediated pyroptosis in ovarian cancer cell lines." (PMID 35778597, 2022). "The cytotoxic effect of a-NETA was strongly blocked by knockdown of either GSDMD or caspase-4 in ovarian cancer cells." (PMID 35673561, 2022). "Quercetin provoked the ER stress by directly provoking apoptosis via raised levels of GRP78, CHOP that both of them are markers of ER stress and cleaved caspase 4 that has been recognized as a principal performer in ER-induced apoptosis in ovarian cancer cell lines and primary ovarian cancer cells." (PMID 32175075, 2020).
pancreatic cancer (7 papers, 2022 to 2023). "Finally, to evaluate the risk and prognosis in pancreatic cancer more conveniently using pyroptosis-related genes, we constructed a prognostic model consisting of seven PRGs, including CASP4, GSDMC, NLRP1, PLCG1, IL-18, CASP1 and NLRP2." (PMID 35712482, 2022). "An additional risk model PRG based on more immune-related genes (CASP4, GSDMC, IL-18, NLRP1, NLRP2, PLCG1, TIRAP, and TNF) was developed, which can be used to predict pancreatic cancer prognosis with an accuracy of medium to high." (PMID 37893166, 2023). "Among them, CASP4, TOB1, and CLEC2B were associated with poorer prognosis in pancreatic cancer patients, while FYN showed a correlation with better prognosis." (PMID 37753069, 2023). "CASP4, FYN, TOB1, and CLEC2B exhibited close associations with infiltrating Treg cells in pancreatic cancer, suggesting their involvement in Treg cell functions." (PMID 37753069, 2023). "A recent study predicted the prognosis of pancreatic cancer using a two-gene signature (CASP4 and NLRP1) based on genes related to pyroptosis." (PMID 38048216, 2023). "But it was the limitation of this study that we haven’t conducted experiments to investigate whether the expression of CASP4/NLRP1 influenced the sensitivity of pancreatic cancer to these drugs., such as comparing tumor growth by using MEK or AKT inhibitors in vivo with animals." (PMID 35633405, 2022). "In addition to pyroptosis, CASP4 may promote pancreatic cancer cell migration by promoting fatty acid synthesis, as well as NLRP1 was also closely related to the RAS/ERK signaling pathway." (PMID 35633405, 2022). "According to this study, PRGs risk models were defined with the combination of immune and signaling pathways genes (CASP4, GSDMC, NLRP1, PLCG1, IL-18, CASP1, and NLRP2), among which CASP4, NLRP1, PLCG1, IL-18, and CASP1 are overexpressed in pancreatic cancers." (PMID 37893166, 2023). "In vitro, CCK8 and Transwell assay suggested that CASP4 may accelerate the progression of PDAC by promoting proliferation and migration of pancreatic cancer cells, while NLRP1 has been found to have tumor suppressive effect." (PMID 35633405, 2022). "Finally, we investigated the relationship between CASP4 and NLRP1 expression levels and drug sensitivity in pancreatic cancer cells." (PMID 35633405, 2022). "Finally, high expression of CASP4 and low expression of NLRP1 increased the sensitivity of pancreatic cancer cells to ERK inhibitors." (PMID 35633405, 2022). "In our study, CCK8 and transwell assay suggested that CASP4 may accelerate the progression of PDAC by promoting proliferation and migration of pancreatic cancer cells." (PMID 35633405, 2022).